TLR4 (toll like receptor 4)
Diseases named in the same sentence as TLR4 in open-access papers (continued):
Sharing a sentence is not in itself a finding about the gene and the disease.
bronchiolitis (11 papers, 2009 to 2025). Inflammation of the bronchioles characterized by swelling of the bronchioles and mucus accumulation. "This study evaluated the interaction between the presence of TLR4 gene polymorphisms and Ascaris infection with severe bronchiolitis in a tropical Colombian region." (PMID 35573947, 2022). "To identify interaction between severe bronchiolitis and presence of TLR4 polymorphisms and Ascaris infection, we used log-binomial regression." (PMID 35573947, 2022). "We concluded that in our population there is an interaction between the presence of severe bronchiolitis, TLR4 Asp299Gly and Ile399Thr polymorphisms, anti-Ascaris IgE levels and RSV." (PMID 35573947, 2022). "In infants with respiratory syncytial virus (RSV) acute infection and positive anti-Ascaris IgE, TLR4 Asp299Gly was associated to low risk of severe bronchiolitis (OR 0.09, CI 95% 0.01–0.48)." (PMID 35573947, 2022). "OR for severe bronchiolitis: association with TLR4 mutation according to anti-Ascaris IgE Levels and RSV." (PMID 35573947, 2022). "In our population there is an interaction between the presence of severe bronchiolitis, TLR4 Asp299Gly and Ile399Thr polymorphisms, anti-Ascaris IgE levels and RSV." (PMID 35573947, 2022). "Among the nine studied TLRs, only TLR7 rs179008 showed some exploratory associations with post-bronchiolitis lung function deficiency, and polymorphisms of TLR4 rs4986790, and TLR6 rs5743810 in particular, with airway reactivity." (PMID 26741133, 2016). "The associations of TLR4 896A>G with hearing loss in survivors of bacterial meningitis and the increased risk of tympanostomy among toddlers with history of bronchiolitis are indicative examples." (PMID 24282567, 2013). "Once activated, it plays a crucial role in inducing the expression of genes related to inflammatory responses in innate immunity by detecting the expression levels of miR-26b and TLR4 mRNA in peripheral blood monocytes from infants with bronchiolitis caused by RSV infection." (PMID 40508053, 2025). "RSV upregulates TLR4 in airway epithelial cells and monocytes among children with acute bronchiolitis." (PMID 38835761, 2024). "We have earlier studied the TLR1rs5743618, TLR2 rs5743708, TLR3 rs3775291, TLR4 rs4986790 and TLR6 rs5743810 polymorphisms, and reported their associations with bronchiolitis and post-bronchiolitis outcomes." (PMID 27498757, 2016). "Conversely, in infants RSV negative with negative anti-Ascaris IgE, TLR4 Asp299Gly was associated with an increased risk of severe bronchiolitis (OR 14.5, CI 95% 2.2–96)." (PMID 35573947, 2022). "Conversely, in infants with negative anti-Ascaris IgE levels, TLR4 Asp299Gly was associated with higher risk of severe bronchiolitis independent of the presence or absence of RSV infection." (PMID 35573947, 2022). "In infants with positive anti-Ascaris IgE levels, TLR4 Asp299Gly was associated with low risk of severe bronchiolitis independent of the presence or absence of RSV infection." (PMID 35573947, 2022). "In vitro studies on human peripheral macrophages suggest that TLR4 recognizes the RSV F protein, and bronchoalveolar lavage analyses have demonstrated elevated neutrophil levels in children with severe bronchiolitis." (PMID 38835761, 2024). "TLR4 rs4986790 genotypes and baseline IOS (z-scores) and exercise-induced changes (z-scores) in the 98 former bronchiolitis patients." (PMID 26741133, 2016). "We propose that targeting the binding of TLR-4 by F protein could potentially lead to novel therapeutic approaches to help control RSV-induced inflammatory consequences and pathology of viral bronchiolitis." (PMID 25856628, 2015).
enteritis (11 papers, 2014 to 2025). Inflammation of the small intestine. "This indicates that TLR4 signaling underlies the majority of the enteritis seen in this model, whereas TLR2 signaling had a protective role, acting to promote mucosal integrity." (PMID 25033044, 2014). "The interaction relationship between Lactobacillus johnsonii and rotavirus is currently unclear, but it can alleviate enteritis by inhibiting the TLR4/NF-κB signaling pathway, which also indicates its potential for anti-RV and alleviating intestinal damage." (PMID 41532082, 2025). "Following peroral infection of TLR4−/−Sigirr−/− mice, C. jejuni colonized the intestines at high levels, but induced rather mild, if any, signs of enteritis." (PMID 32231139, 2020). "For the RS diet treatment, a trend of increased (P = 0.083) Tlr4 expression was observed in mice with enteritis relative to those consuming the WB diet." (PMID 28031748, 2016). "For example, kaempferol inhibits the activation of inflammatory NF-κB transcription factors through NIK/IKK and MAPKs in aged rat kidneys, meanwhile, kaempferol alleviates enteritis in mice by inhibiting the kaempferol alleviates enteritis in mice by inhibiting the TLR4/NF-κB." (PMID 39723150, 2024). "Additionally it was shown that E. coli LPS triggers TLR-4-signalling, which is a key signal for initiation and continuation of enteritis." (PMID 24413899, 2014). "Clinical studies revealed that enteritis and post-infectious morbidities of human C. jejuni infections are strongly dependent on the structure of pathogenic lipooligosaccharides (LOS) triggering the innate immune system via Toll-like-receptor (TLR)-4 signaling." (PMID 32231139, 2020).
enterocolitis (11 papers, 2007 to 2026). An inflammatory process affecting the small intestine and colon. "Some studies have shown that TLR4 knockout mice did not develop enterocolitis upon treatment with DSS and TLR4 antagonist antibody ameliorates inflammatory response in colitic mice." (PMID 24325678, 2013).
gestational diabetes mellitus (11 papers, 2014 to 2025). "SIN has therapeutic effects in streptozotocin-induced gestational diabetes mellitus (GDM) rats with high safety, which is associated with the inhibition of inflammation and oxidative stress via the TLR4/MyD88/NF-κB signaling pathway." (PMID 41200108, 2025). "In models of gestational diabetes mellitus, increased immune markers, including TLR4, TLR5, IL-22, and IL-23, have been detected in the placenta, suggesting a role for TLR4 and TLR5 in the inflammatory processes associated with maternal metabolic disturbances." (PMID 40558558, 2025). "CSF alleviated gestational diabetes exacerbation and metabolic dysfunctions in mice by suppressing the TLR4/NF-κB pathway, as evidenced by the decrease in TLR4 and p-p65." (PMID 37762063, 2023). "TLR-4-induction of NFκB signaling in the placenta is an important mechanism that is altered during gestational diabetes; however, further studies are needed to elucidate the involvement of innate immunity in trophoblast functionality." (PMID 34360849, 2021). "Taken together, this evidence implied that targeting NF-κB and relevant cross-talk, including TLR4, SIRT1, and ERK1/2, might be the possible mechanism of CSF in relieving DM, DN, DR, diabetic cardiovascular diseases, and gestational diabetes." (PMID 37762063, 2023). "However, whether TLR4 is expressed in patients with gestational diabetes mellitus (GDM) has not been elucidated." (PMID 24348797, 2014).
head and neck cancer (11 papers, 2011 to 2026). A primary or metastatic malignant neoplasm affecting the head and neck. "In head and neck cancer, resistance is also mediated by TLR4-MyD88 signaling activation, loss of tumor suppressor genes like PTEN, activating mutations in PI3K, and involvement of STAT3." (PMID 40560045, 2025). "According to this study, TLR4 299Gly und 399Ile alleles may serve as markers for prognosis of head and neck cancer in patients with adjuvant systemic therapy, particularly chemotherapy, and might indicate therapy resistance." (PMID 21854645, 2011). "The data from TCGA showed that TLR4 is expressed in head and neck cancer as a non-mutated diploid occurrence (~96%), indicating that the TRL receptor can serve as a functional receptor, especially in HPV (+) tumors." (PMID 37174723, 2023). "TLR4 activation has been described to mediate anti-EGFR therapy resistance in head and neck cancer." (PMID 36551979, 2022). "TLR4 affected the survival of head and neck cancer due to poor oral hygiene." (PMID 30865385, 2019). "In a transplantable model of orthotopic head and neck cancer in C3H mice, the absence of TLR4 on host cells resulted in accelerated tumour growth." (PMID 28300057, 2017). "Moreover, patients with head and neck cancer responded to OK-432 treatment combined with fluoropyrimidine chemotherapy and radiation significantly better if they expressed TLR4 and MD-2 mRNA (compared to patients without TLR4 or MD-2 expression)." (PMID 22110526, 2011).
metastatic disease (11 papers, 2009 to 2025). "Univariate cox regression analysis also revealed an association between TLR4+/pSTAT3− PBMCs and a high risk of death in patients with metastatic disease (HR: 3.061; 95% CI: 1.378–6.796; p = 0.006)." (PMID 35205801, 2022). "All polymorphisms detected were also significantly associated with the metastatic disease (p<0.001) leading to shorter overall survival (p<0.001); whereas, TLR4 Asp299Gly and Thr399Ile polymorphisms were significantly associated with KRAS mutations." (PMID 29883450, 2018). "In cancers, high nuclear and cytoplasmic staining of TLR4 associated with metastatic disease and poor prognosis." (PMID 27008696, 2016). "In addition, TLR4+/pSTAT3− PBMCs independently predict high risk of death among patients with metastatic disease." (PMID 35205801, 2022). "In particular, we show that TLR4 expression on PBMCs predominates in metastatic disease, whereas pSTAT3 is more frequently expressed in the early disease setting." (PMID 35205801, 2022). "There was a positive correlation between the percentages of TLR4 and pSTAT3 expression on PBMCs in both early and metastatic disease settings (p = 0.001 and p = 0.025, respectively; Spearman’s rho correlation)." (PMID 35205801, 2022). "Regarding PBMCs, TLR4 expression prevailed in metastatic disease (p = 0.029), while pSTAT3 expression was more frequent in early disease (p = 0.014)." (PMID 35205801, 2022). "It has been speculated that TLR4 was downregulated and TLR2 was upregulated in CRC patients, and low expression of TLR4 in the invasive front predicts poor prognosis and metastatic disease." (PMID 39073297, 2024). "However, notably, PBMCs positive for TLR4 only (TLR4+/pSTAT3−) were detected in metastatic disease only (0% vs. 7% of patients; p = 0.007)." (PMID 35205801, 2022). "Moreover, HMGB1 binding to Toll-like receptor 4 seemed to be critical for the oxaliplatin efficacy, since patients carrying a loss-of-function TLR4 allele had impaired progression-free survival (PFS) when given oxaliplatin for metastatic disease." (PMID 32781554, 2020). "Moreover, ADAM22 expression correlated with known brain metastatic associated in both primary (MOCS1, n = 21, p < 0.05) and metastatic tumours (MOCS1, COL13A1, TLR4, HBEGF and PELI2, n = 21, p < 0.05)." (PMID 33208158, 2020). "Furthermore, a lower serum TLR4 concentration has been reported in patients with metastatic tumors than in those with nonmetastatic tumors." (PMID 40878805, 2025).
prostate tumor (11 papers, 2012 to 2025). "Chronic activation of Toll-like receptor 4 (TLR4) signaling within the prostate tumor microenvironment is a recognized driver of disease progression, linking innate immune activation to oncogenic processes." (PMID 41162970, 2025). "Inhibition of the rapid endocytotic uptake of Ahsg was demonstrated in TLR4-knockdown prostate tumor cells treated with a TLR4-specific inhibitor (CLI-095), which inhibited tumor cell adhesion and invasion through Matrigel." (PMID 39684629, 2024). "In addition, TLR4 is known to induce VEGF expression in prostate tumors related to interaction with hypoxia inducible factor-1 α (HIF-1α); VEGF enhances the nuclear factor kappa-light-chain-enhancer of activated B cells (NF-κB) in the tumor microenvironment." (PMID 36829917, 2023). "In contrast to our observations, one study shows that ligation of TLR4 with LPS induced increased resistance to the growth inhibitory effects of docetaxel on PC-3 prostate tumor cells, and other groups have shown that TLR4 activation is associated with increased resistance to taxanes in SKOV-3." (PMID 28915246, 2017). "Rapid uptake of fetuin‐A was inhibited by the specific TLR4 inhibitor CLI‐095 and also attenuated in TLR4 knockdown prostate tumor cells." (PMID 33073533, 2020). "This novel PRDX1‐TLR4‐ HIF‐1α pathway can be targeted by TLR4 inhibitors and can perhaps serve as a therapeutic target in the treatment of PRDX1‐driven prostate tumour angiogenesis." (PMID 27653015, 2017). "We showed that, in spite of the absence of surface expression of TLR2 and TLR4, prostate tumor cells are responsive to LPS and LTA implying that activation is mediated through ligand internalization." (PMID 24966802, 2014).
skin cancer (11 papers, 2017 to 2025). "Our findings contribute to the limited information on how TLR4 SNPs can influence susceptibility to skin cancer." (PMID 39684439, 2024). "There is limited information available on the association between TLR4 SNPs and the risk of skin cancer." (PMID 39684439, 2024). "Our ongoing studies using a D299G/T399I TLR4 SNP mouse model have revealed a protective role of this SNP in UV-induced immune suppression, which is a major risk for skin cancer." (PMID 39684439, 2024). "Multivariable logistic regression models were used to assess the association between TLR4 SNPs and skin cancer risk." (PMID 39684439, 2024). "The absence of the T399I SNP in cases and the identification of a novel K354K variant highlight the complex genetic landscape of TLR4 in relation to skin cancer risk." (PMID 39684439, 2024). "Our study adds to this body of knowledge by specifically examining the relationship between TLR4 SNPs and skin cancer risk." (PMID 39684439, 2024). "In this study, we investigated the association between TLR4 SNPs D299G and T399I and the risk of developing skin cancer in a cross-sectional case–control study in patients seen at the Dermatology Clinic at the University of Alabama at Birmingham." (PMID 39684439, 2024). "In contrast to UV carcinogenesis in which TLR4 deficient mice are resistant to skin tumor development, TLR4 deficient mice are more prone to chemically induced carcinogenesis." (PMID 34771569, 2021). "Studies in TLR4-deficient mice revealed that TLR4 has a supportive role in the development of chemically induced skin cancer through immune response." (PMID 28982115, 2017). "However, further research is needed to fully elucidate the relationship between TLR4 genetic variations and skin cancer susceptibility." (PMID 39684439, 2024). "In conclusion, our study suggests a potential protective effect of the TLR4 D299G/T399I SNP against skin cancer." (PMID 39684439, 2024). "The sample consisted of a cohort of 93 skin cancer patients over the age of 50 and 94 controls; 33.3% of cases and 44.7% of controls were females; 12.9% of cases and 17% of controls had a TLR4 SNP." (PMID 39684439, 2024). "A total of 187 subjects were typed successfully (93 skin cancer patients and 94 controls) for TLR4 D299G (A>G at the DNA level) and T399I (C>T at the DNA level) polymorphisms." (PMID 39684439, 2024). "Our findings, which suggest a potential protective effect of TLR4 SNPs, align more closely with the latter study and underscore the nuanced and context-dependent role of TLR4 in skin cancer development." (PMID 39684439, 2024). "Additionally, investigating the interaction between TLR4 SNPs and environmental factors, such as UV exposure, and assessing the early biomarkers of cancer could provide a more comprehensive understanding of skin cancer risk." (PMID 39684439, 2024). "Future studies should aim to replicate these findings in larger cohorts and explore the functional implications of TLR4 SNPs in skin cancer development." (PMID 39684439, 2024). "Studies from our laboratory have shown that the activation of TLR4 can have a protective effect on chemically induced skin tumors in mice." (PMID 39684439, 2024). "In the present study, we addressed the mechanism elicited by which TLR4 inhibitor TAK-242 prevent the development of UVB-induced skin tumors." (PMID 34771569, 2021). "A study recently reported that decursin displayed anti-inflammatory activity via down-regulation of the TLR4/JNK signaling pathway provoked by PRP4 expression in lipopolysaccharide (LPS)-induced skin cancer (B16–F10) cells." (PMID 32823713, 2020). "Alteration of TLR4 signaling due to the presence of SNPs can influence the DNA repair process and clearance of mutant cells, resulting in the progression or inhibition of skin tumor development." (PMID 39684439, 2024). "TLR4 is highly expressed in human skin tumors compared to normal skin." (PMID 34771569, 2021).
skin cancer (continued). "In addition, TLR4 has been found to have antitumor activity in skin cancer." (PMID 36030212, 2022). "Toll-like receptor-4 (TLR4)-mediated immune dysregulation has emerged as a key mechanism for the detrimental effects of acute and chronic UV exposure and skin cancer in mice." (PMID 39684439, 2024). "In the present study and those of others, TLR4 antagonist, TAK-242 was effective in prevention of UVB-induced skin cancer in animal models and pave the way for clinical trials in which TAK-242 is evaluated for prevention of UV-induced skin cancer." (PMID 34771569, 2021). "In this study, we determined the mechanism through which TLR4 inhibitor TAK-242 regulates inflammation and prevents skin cancer." (PMID 34771569, 2021). "Moreover, treatment with the TLR4 inhibitor TAK-242 may be effective for prevention of skin cancer." (PMID 34771569, 2021). "Toll-like receptor-4 (TLR4) and NLR family pyrin domain containing 3 (NLRP3) belong to the family of innate immune receptors and are highly expressed in skin tumors." (PMID 34771569, 2021). "Based on our findings from our limited cohort of participants, we found some protective effect for the TLR4 SNP for skin cancer, which was not statistically significant." (PMID 39684439, 2024). "A recent study proved that TLR4-mediated inflammation may potentiate the effects of UVB and even increase the incidence of UVB-induced skin cancers." (PMID 34468896, 2021).
stomach adenocarcinoma (11 papers, 2015 to 2025). "TLR4 polymorphisms, expression, and VitD could be implicated in H. pylori infection and further development of gastric adenocarcinoma." (PMID 30641993, 2019). "Although the expression of TLR4 was more elevated in stomach adenocarcinoma tissues than in normal tissues, this discrepancy was not significant." (PMID 36281200, 2022). "Finally, the pre-incubation of the human gastric adenocarcinoma cell line AGS with blocking antibodies against Toll-like receptor-2 (TLR2), but not TLR4, prevented HIF-1α induction." (PMID 31185594, 2019).